CXCR4 (C-X-C motif chemokine receptor 4)
Diseases named in the same sentence as CXCR4 in open-access papers (continued):
Sharing a sentence is not in itself a finding about the gene and the disease.
autoimmune disease (46 papers, 2008 to 2026). A disorder resulting from loss of function or tissue destruction of an organ or multiple organs, arising from humoral or cellular immune responses of the individual to their own tissue constituents. "In this context, the association between aab targeting CXCR3 and CXCR4 remained stable despite the presence of autoimmune diseases." (PMID 30523250, 2018). "Given that women are at significantly greater risk of developing autoimmunity diseases, targeting the CXCR4 anti-inflammatory pathway may therefore represent a particularly effective strategy for these pathologies." (PMID 39737176, 2024). "In summary, the CXCR4/CXCL12 axis represents a shared immune dysregulation pathway connecting multiple autoimmune diseases." (PMID 41481752, 2026). "Cxcr4 plays a role in leukocyte chemotaxis during inflammatory conditions in various autoimmune diseases, and elevated levels of Cxcr4 have been observed in various types of human cancers." (PMID 40440080, 2025). "Clobenpropit is a histamine H3 receptor antagonist and has developed as a potential therapeutic drug due to its ability to inhibit CXCR4, a chemokine receptor involved in autoimmune diseases and cancer pathogenesis." (PMID 39070795, 2024). "Accordingly, inhibiting CXCR4 can have promising clinical outcomes in patients with malignancy or autoimmune disorders." (PMID 39070795, 2024). "Upregulation of CXCR4 expression and dysregulation of CXCR4/CXCL12 axis have been described in autoimmune diseases in particular in SLE." (PMID 39737176, 2024). "Gaining a more comprehensive understanding of the CXCR4 minor pocket’s role and function is thus an intriguing research avenue, with the aim of potentially turning it into a therapeutic target in autoimmune diseases." (PMID 38519141, 2024). "The rare autoimmune disease WHIMS is caused by impaired desensitization and internalization of CXCR4, leading to enhanced chemotactic responsiveness to CXCL1263." (PMID 37736772, 2023). "ACKR3 is an atypical chemokine receptor associated with some autoimmune diseases and inflammatory responses, and the CXCL12/CXCR4/ACKR3 axis is a potential therapeutic target for several inflammatory diseases." (PMID 36118358, 2022). "Although numerous studies indicated that CCL5 and CXCR4 played an important role in the progression of many diseases, including chronic liver disease, malignant tumor, and autoimmune disease, the specific mechanism needs to be further explored." (PMID 34484236, 2021). "Recently, the CXCL12/CXCR4/CXCR7 axis was associated with cancer metastasis and autoimmune diseases." (PMID 34764871, 2021). "That HMGB1 with the receptors CXCL12 and CXCR4 is also involved in autoimmune diseases has already been reported." (PMID 34943212, 2021). "Although CXCR4 blockade benefits to autoimmune diseases, it is deleterious in acute inflammation and ischemia, and has a negative impact on negative physiological defense." (PMID 33013914, 2020). "Similar to CXCR4, ACKR3 is implicated in some autoimmune diseases, such as rheumatoid arthritis, inflammatory bowel disease, and experimental autoimmune encephalomyelitis (EAE)." (PMID 31507535, 2019). "Here, we review the involvement of the CXCL12/CXCR4/ACKR3 axis in some of the most prevalent autoimmune diseases: psoriasis, multiple sclerosis, rheumatoid arthritis, lupus, type I diabetes (T1D), and inflammatory bowel disease." (PMID 31507535, 2019). "Due to growing evidence that supports an important role for CXCR4 in tumor progression, stem and progenitor cell mobility and autoimmune diseases, CXCR4 gained broad attention as an attractive target for therapeutic intervention in various disease areas." (PMID 28410420, 2017). "In mouse models of autoimmune disease, modulation of CXCR4 alters trafficking of leukocytes to peripheral organs and polarization of regulatory T cells, and accelerates onset of disease." (PMID 27005825, 2016).
autoimmune disease (continued). "CXCR4 is involved in B-cell differentiation and homing as well as in the inflammatory development and progression of B-cell mediated autoimmune disorders including SLE." (PMID 23244336, 2012). "Involvement of the CXCR4/CXCL12 axis is also reported in other autoimmune diseases." (PMID 38519141, 2024). "In treating CNS autoimmune diseases, the findings suggest that targeting both CXCR4 and CXCR3 simultaneously may be beneficial." (PMID 39070795, 2024). "Furthermore, chemokine CXCR4 functions as a proinflammatory factor in autoimmune diseases and inflammatory diseases, and suppression on its expression is considered to be a candidate plan for the treatment of such diseases." (PMID 34630628, 2021). "CXCR4 and CXCL12 have been implicated in the pathogenesis of autoimmune diseases." (PMID 27005825, 2016). "Our results suggest the association of CXCR4 variants with JIA, implicating that this gene may be involved in the pathogenesis of autoimmune disease." (PMID 27005825, 2016). "SDF-1/CXCR4 interaction recruits inflammatory cells to the injury site, exacerbates inflammation and thus plays an important role in the pathogenesis of autoimmune diseases, idiopathic lung fibrosis, bleomycin-induced lung injury, and possibly in acute graft versus host disease." (PMID 20596257, 2010). "Although the precise mechanism underlying the discrepancy between the two studies has yet to be determined, our finding provides a basis for further exploring the use of AMD3100 to prevent and/or treat TID and possibly other autoimmune diseases in patients with elevated CXCL12 or CXCR4 expression." (PMID 18793419, 2008). "However, few data are available on the role of CXCR4 in B cell–mediated autoimmune diseases." (PMID 38519141, 2024). "Therefore, inhibiting CXCR4 by Clobenpropit could reduce the pathologic effects of dysregulated pDC-derived IFNs-I production in inflammatory and autoimmune diseases." (PMID 39070795, 2024). "Moreover, compared to rN and IM cells, aN and dnCS B cells in APs expressed a lower level of CXCR4, which is critical for GC reaction, and higher level IL‐21R, which promotes B cells to differentiate into PBs through the EF pathway in autoimmune disease." (PMID 36103567, 2022). "Also, CXCR4 is intensively studied in different autoimmune diseases, including rheumatoid arthritis, systemic lupus erythematosus, and autoimmune disorders of the central nerve system as multiple sclerosis, for its involvement in leukocyte chemotaxis in specific inflammatory conditions." (PMID 24966838, 2014). "The chemokine CXCL12 and its two cognate receptors—CXCR4 and ACKR3—are key players in various homeostatic and pathophysiological processes, including embryonic development, autoimmune diseases, tissue repair, and cancer." (PMID 39662834, 2024). "MIF is known to be involved in the progression of inflammatory and autoimmune diseases and interacts with various receptors, including CXCR2, CXCR4, and CD74 (Bucala 2013, Morrison and Kleemann 2015)." (PMID 37740953, 2023). "As a proinflammatory mediator secreted by numerous immune cells, MIF promotes inflammation and autoimmune diseases mainly by binding with the receptor CD74 and co-receptor CD44, CXCR4, or CXCR2." (PMID 36046240, 2022). "There is a high expression of CXCR4 on CD4+ T cells, contributing to the migration of CD4+ T cells to pancreatic islets and destruction of β cells in T1D and other autoimmune diseases." (PMID 32878069, 2020). "The present review discusses the role of the CXCL12/CXCR4/ACKR3 axis in inflammation, focusing on its involvement in several autoimmune diseases." (PMID 31507535, 2019). "The chemokine CXCL12 (SDF-1) and its cognate receptor CXCR4 are involved in a large number of physiological processes including HIV-1 infectivity, inflammation, tumorigenesis, stem cell migration, and autoimmune diseases." (PMID 27456816, 2016).
autoimmune disease (continued). "Our data support a role for altered expression of CXCR4 in JIA pathogenesis, and present the first genetic demonstration of a potential role for the chemokine receptor, CXCR4, in the pathogenesis of autoimmune disease." (PMID 27005825, 2016). "Indeed, this cytokine is able to recruit and promote the accumulation of leukocytes via CXCR4/CXCR784 and participates in the organization of ectopic secondary lymphoid follicles that takes place in autoimmune diseases, such as in AITD85,86." (PMID 39003267, 2024). "CXCR4, known as SDF-1α receptor, plays a critical role in normal physiology as well as the pathology of many human diseases including cancer, inflammation, and autoimmune disease." (PMID 25852766, 2015). "Given its pivotal involvement in B-cell homeostasis, and beyond its extensively documented role in B-cell lymphoproliferative disorders, CXCR4 can play a contributory role, if not a central one, in non-malignant B-cell disorders, ranging from immunodeficiencies to autoimmune diseases." (PMID 38519141, 2024).
Immunodeficiency (46 papers, 2009 to 2026). Failure of the immune system to protect the body adequately from infection, due to the absence or insufficiency of some component process or substance. "The “warts, hypogammaglobulinemia, infections, and myelokathexis” syndrome is an inherited immune disorder caused by an autosomal dominant heterozygous mutation in CXCR4." (PMID 38331475, 2024). "Warts, hypogammaglobulinemia, infections, and myelokathexis (WHIM) syndrome (WS) is a combined immunodeficiency caused by gain-of-function mutations in the C-X-C chemokine receptor type 4 (CXCR4) gene." (PMID 35947323, 2022). "CCR5 (R5) tropic viruses are associated with early stages of infection, whereas CXCR4 (X4) HIV-1 tropism has been associated with severe immunodeficiency." (PMID 26297538, 2015). "The virus phenotype of the infected children, like that of adults, can evolve from R5 to CXCR4-using phenotype or remain R5 despite clinical progression to overt immune deficiency." (PMID 21284900, 2011). "On the contrary, in another study accurate sampling throughout the disease showed that CXCR4-using viruses possibly emerge in some children as a consequence of the severe immune deficiency." (PMID 21284900, 2011). "It should be noted that during severe immune deficiency, when CXCR4-tropic HIV is most prevalent, risks for Kaposi sarcoma and central nervous system lymphoma are very high despite tumor expression of CXCR4." (PMID 21179547, 2010). "WHIM (warts, hypogammaglobulinemia, infections, and myelokatexis) syndrome is a rare immunodeficiency syndrome linked to heterozygous mutations of the chemokine receptor CXCR4 resulting in truncations of its cytoplasmic tail." (PMID 19956569, 2009). "Furthermore, the compound was shown to block CXCR4-based signaling in a specific and reversible manner propelling its potential utility in the treatment of immune dysfunctions caused by HIV and cancers." (PMID 39146384, 2024). "WHIM (warts, hypogammaglobulinemia, infections, and myelokathexis) syndrome is a rare disease, caused by CXCR4 gene mutations, which incorporates features of combined immunodeficiency, congenital neutropenia, and a predisposition to human papillomavirus infection." (PMID 34697698, 2022). "However, if it is now well established knowledge that the CXCR4-using phenotype is associated with a severe state of immune deficiency, its predictive value is still controversial." (PMID 21284900, 2011). "The role of CXCR4 in various diseases, including cancer, autoimmunity, and immunodeficiencies, has been well-documented." (PMID 41222235, 2025). "Taken together, these findings support the involvement of CXCR4 in the development and progression of immunodeficiency, inflammatory diseases and cancer and highlight its potential as a therapeutic target." (PMID 39035006, 2024). "Consistent with this, the prominent role of CXCR4 in immunodeficiencies has been largely documented." (PMID 32784523, 2020). "Inherited heterozygous autosomal dominant mutations in the CXCR4 gene cause WHIM syndrome, a severe combined immunodeficiency disease characterized by susceptibility to human papilloma virus infection, which causes warts, condyloma acuminata and carcinomas." (PMID 31507535, 2019). "Overall, these data illustrate the involvement of the CXCR4/CXCL12 axis in the development and progression of immunodeficiency and inflammatory diseases and cancer, and underline its interest as a target for therapeutic intervention." (PMID 31507535, 2019). "Because gp120/CXCR4-induced lymphocyte death leads to pathological immunodeficiency, a lot of research is still ongoing to identify a CXCR4 antagonist that would selectively prevent the gp120/CXCR4 interaction and thereby HIV-triggered disease progression." (PMID 26347749, 2015).
Immunodeficiency (continued). "The functional importance of the CT tail of CXCR4 has been underscored by identification of truncating mutations of CXCR4 in patients with WHIM (warts, hypogammaglobulinemia, immunodeficiency, and myelokathexis) syndrome." (PMID 21124917, 2010). "Fortunately, when CXCR4 blockers or HAART are used in conjunction with CCR5 blockers, this risk of accelerated immunodeficiency is eliminated." (PMID 19680436, 2009). "Data suggest that viral use of CXCR4 correlates with immunodeficiency and progression to AIDS." (PMID 39035006, 2024). "This is reminiscent of dominant mutations in CXCR4, responsible for WHIM (warts, hypogammaglobulinemia, immunodeficiency, and myelokathexis) syndrome, that lead to enhanced and prolonged β integrin activation responsible for accumulation of mature and degenerating neutrophils in the BM." (PMID 39225097, 2024). "Using protein delivery allows for the cells to have an advantage during the critical homing time period but does not risk causing future immunodeficiency resulting from permanent CXCR4 upregulation." (PMID 35531956, 2022). "Fine tuning of CXCR4 responses is critical for normal ASC localization, as illustrated by the effects of mutations in CXCR4 in mice that copy the gain-of-function mutations observed in warts-hypogammaglobulinemia-immunodeficiency-myelokathexis syndrome." (PMID 30642980, 2019). "In the course of this study, we noted a markedly decreased expression of the chemokine receptor CXCR4 at the surface of CD4+ T cells from ICL patients, suggesting that impaired CXCR4-dependent cell trafficking may contribute to the immunodeficiency." (PMID 23383227, 2013). "However, CCR5 inhibitors do not appear to have the deleterious effect of accelerating X4 emergence and immunodeficiency when they are used in conjunction with CXCR4 inhibitors or HAART." (PMID 19680436, 2009). "Although we cannot dismiss the hypothesis that the WS immunodeficiency eventually affects anti-HPV immune responses, we rather favor the possibility that the CXCL12/CXCR4 axis represents a host susceptibility factor for HPV-infection and associated carcinogenic evolution." (PMID 23009155, 2012). "A previous study showed that CXCR4 was upregulated in naive CD4+ and CD8+ T cells and CD4+ central memory T cells, which have a crucial role in modulating immune dysfunction." (PMID 32983229, 2020). "Because CXCR4 and CCR5 are found on different CD4+ T cells, X4 depletes a second set of critical immune cells, accelerating immunodeficiency and death." (PMID 19680436, 2009). "Both endogenous and therapeutic corticosteroids can transiently reduce circulating eosinophils through CXCR4-dependent bone-marrow homing, indicating systemic stress and inflammatory burden rather than persistent immune dysfunction." (PMID 41300914, 2025). "Of interest, the low expression of CXCR4 as well as the class-A1 Rhodopsin-like receptors in COVID-derived CD4+ naïve T cells resulted in a reduced responsiveness of the IL-10 signaling pathway, which may contribute to immunodeficiency in patients." (PMID 34944610, 2021). "Finally, generalizing across kM4 and kM5 parameter space shows that when treatment efficacies are sufficiently strong (e.g. 80% efficacies) dual treatment with CXCR4 inhibitors does not accelerate immunodeficiency relative to untreated individuals." (PMID 19680436, 2009). "Given that CCR5 inhibitors accelerate R5-to-X4 switching and immunodeficiency across the wide swath of parameter space in which kM4 is relatively large, the question arises as to whether CCR5 inhibitors are similarly deleterious when used in conjunction with CXCR4 inhibitors, which reduce kM4." (PMID 19680436, 2009).